LBP (lipopolysaccharide binding protein)
Diseases named in the same sentence as LBP in open-access papers (continued):
Sharing a sentence is not in itself a finding about the gene and the disease.
bacterial infection (45 papers, 2009 to 2025). "LBP is involved in the innate immune response to bacterial infections and MTA1 encodes a transcriptional coregulator upregulated in numerous cancer types and associated with cancer progression." (PMID 35078996, 2022). "LBP aids the immune response to bacterial infections by binding LPS, enabling its detection by CD14 and Toll-like receptors, which initiate inflammation." (PMID 40027189, 2025). "LBP is an acute-phase protein synthesised by hepatocytes in response to bacterial infection and endotoxins; its secretion increases with intestinal barrier disruption." (PMID 40777179, 2025). "In the resistance assay of Trachinotus ovatus to bacterial infection, LBP exhibited antibacterial and binding activity against Gram-negative bacteria." (PMID 38891754, 2024). "It is a receptor of lipopolysaccharide–lipopolysaccharide-binding protein (LPS-LBP) complexes, transducing the endotoxin signal from bacterial infection through the Toll-like receptor-4." (PMID 34983420, 2022). "Lipopolysaccharide binding protein (LBP) gene is involved in the acute-phase immunologic response to bacterial infections in Nile tilapia against Streptococcus agalactiae and Aeromonas hydrophila." (PMID 34359162, 2021). "LBP is one of the acute phase immunologic response proteins for bacterial infection known to be involved in regulating LPS-dependent monocyte response." (PMID 28450824, 2017). "In fact, we observed high concentrations of LBP in serum derived from some patients with bacterial infections (G2)." (PMID 28262744, 2017). "Pro- and anti-inflammatory properties of Lf in bacterial infections have been ascribed to its ability to act as a LPS-binding protein (LBP)." (PMID 28257033, 2017). "The concentration of lipopolysaccharide-binding protein (LBP) is increased during bacterial infections." (PMID 22348735, 2012). "LBP has been reported to be a biomarker for the diagnosis of local bacterial infection and LBP is involved in LPS-induced tight junction disruption and increased permeability in bile duct epithelial cells." (PMID 22299632, 2012). "In our study, the LBP concentration was the best parameter to differentiate between typical and atypical or viral pathogens, and we found significantly higher LBP concentrations in patients with typical bacterial infections." (PMID 22348735, 2012). "Within the group of typical bacterial infections, we found higher LBP concentrations in patients infected with Gram-positive bacteria." (PMID 22348735, 2012). "LBP plays a dual role in the innate immune response to bacterial infection and inflammation." (PMID 40508008, 2025). "LBP encodes the lipopolysaccharide-binding protein that plays an essential part in both innate immunity against bacterial infections and will protect the host from Gram-negative bacteria." (PMID 38891754, 2024). "Soluble LPS receptors, and especially LBP levels, are enhanced after bacterial infections." (PMID 37240201, 2023). "In the presence of bacterial infection first, soluble plasma protein LBP binds to LPS whereupon it is recognized by CD14—a glycosylphosphatidylinositol-linked, LRRs-containing protein that delivers LBP-LPS complex to the cell surface." (PMID 35237675, 2022). "Significant increases in LBP, a proposed sensitive acute marker for bacterial infection, were detected one week post-circumcision (week 5 median: 18.2μg/ml, IQR: 15.0–23.1μg/ml) when compared to the day of the procedure (week 4 median: 14.4 μg/ml, IQR: 10.6–21.2μg/ml; p = 0.0121)." (PMID 27536938, 2016). "Other biomarkers with one to two studies showing statistically significant differences in expression levels in bacterial infection patients compared to non-bacterial infection patients include LBP, LCN-2, lactoferrin, sPLA2, D-Lactate in CSF, EDA-FN, FN, and soluble CD14." (PMID 27486746, 2016). "We found significant differences in IL-6, IL-10 and LBP concentrations between patients with unknown pathogens and those with typical bacterial infections." (PMID 22348735, 2012).
bacterial infection (continued). "In addition, significant differences in the LBP concentrations were found in patients with typical (23.25 μg/ml) and atypical bacterial infections (18.7 μg/ml, P < 0.012)." (PMID 22348735, 2012). "At the same time, LBP was found to be an acute phase marker during bacterial infection." (PMID 20886039, 2010). "Furthermore, we measured LBP, a prognostic marker for bacterial infections." (PMID 32825817, 2020). "Therefore, this may indicate that bacterial infections followed by LBP upregulation contribute in part to the onset of KD." (PMID 28262744, 2017). "It is a receptor of lipopolysaccharide–lipopolysaccharide-binding protein (LPS–LBP) complexes, transducing the endotoxin signal from bacterial infection through the Toll-like receptor-4 with the help of thinositol lipid structure." (PMID 28875483, 2017). "Corneal fibroblasts sense bacterial infection through the detection of LPS by TLR with the assistance of sCD14 and LBP in tear fluid." (PMID 28832498, 2017). "Females without bacterial infections had lower plasma LBP levels than males without bacterial infections (p = 0.040)." (PMID 39997462, 2025). "The small number of females with bacterial infection is also a limitation of this analysis and the suitability of plasma LBP as an early marker for Gram-negative infections needs validation in larger cohorts." (PMID 39997462, 2025). "Additionally, with the emergence of molecular diagnostic techniques, promising lipid biomarker such as LPS, LTA, LBP and the immunologic biomarker soluble CD14 subtype, known as presepsin, for the detection of bacterial infections have been found." (PMID 34983426, 2022). "Soluble CD14 bound to LPS and LBP can then bind to endothelial and epithelial cells to activate cytokine secretion thereby allowing nonmyeloid cells a way to respond to bacterial infections." (PMID 36290196, 2022). "Similarly to IL-8, the two members of the tubular lipid binding proteins (TULIP) family lipopolysaccharide binding protein (LBP) and bactericidal/permeability-increasing protein (BPI) are increased in bacterial infections." (PMID 33233831, 2020). "The evolutionary relationship between SPLUNC1 and both LBP and BPI has long invited speculation that SPLUNC1 might have either pro- or anti-inflammatory effects in the context of a bacterial infection or other inflammatory stimulus." (PMID 25765466, 2015). "This supports the previous finding that LBP is a non-specific marker of bacterial infection." (PMID 22348735, 2012).
metabolic disorders (24 papers, 2016 to 2025). "The increase in LBP concentration has been observed in various metabolic diseases, which are linked to changes in gut permeability and alterations in the gut microbiome." (PMID 39859200, 2025). "Single-nucleotide polymorphisms in the LBP gene are associated with infectious diseases, inflammatory disease, metabolic disorders, and malignancy." (PMID 36289608, 2022). "Therefore, the literature shows that LBP and sCD14 are important factors implicated in low-grade inflammation during metabolic diseases." (PMID 32570947, 2020). "Lipopolysaccharide-binding protein (LBP) is closely associated with many metabolic disorders." (PMID 26799617, 2016). "Elevated zonulin facilitates the passage of luminal antigens into the circulation, contributing to systemic inflammation and metabolic disorders, while LBP enhances LPS–CD14–TLR4 interactions, initiating pro-inflammatory signaling." (PMID 41302175, 2025). "In this context, lipopolysaccharide (LPS) and LPS-binding protein (LBP) have emerged as potential mediators in the progression to metabolic disorders and NAFLD." (PMID 38139003, 2023). "We found that elevated plasma lipopolysaccharide binding protein (LBP) was the most important predictor of impaired metabolic health and network analysis showed that LBP formed a hub joining correlated microbial and immune predictors of metabolic disease." (PMID 34006628, 2021). "VSURF selected immune markers that were positively correlated with the metabolic disease score included LBP, intercellular adhesion molecule 1 (ICAM-1), interleukin-16 (IL-16), IL-12, and granulocyte-macrophage colony-stimulating factor (GM-CSF)." (PMID 34006628, 2021). "LBP and sCD14, two important actors in the endotoxin metabolic pathway, are now considered indirect markers of gut permeability in metabolic diseases, but also in other diseases, such as HIV." (PMID 32570947, 2020). "Thus, it is suggested that LBP and sCD14, as well as the ratio to each other, are important factors in low-grade inflammation during metabolic diseases." (PMID 38202282, 2024). "In this context, the LPS/LBP axis has emerged as a potential mediator in the progression from chronic positive energy balance and an unbalanced diet composition to clinically overt metabolic disorders and NAFLD." (PMID 38139003, 2023). "Indeed, despite extensive research, the connection between circulating LBP levels and metabolic diseases, beyond their link to increased body adiposity, remains inconclusive." (PMID 38139003, 2023). "Further data supporting a potential protective role of LBP in metabolic diseases come from experimental rodent models, where liver LBP gene downregulation resulted in a significant increase in the hepatic expression of markers of inflammatory liver injury, regardless of LPS levels." (PMID 38139003, 2023). "In a previous study, the abundance of Faecalibaculum decreased along with serum proinflammatory cytokines and lipopolysaccharide-binding protein (LBP) in HFD-fed mice, suggesting that it is involved in the gut proinflammatory pathway, which is associated with metabolic disorders." (PMID 36017311, 2022). "In a systems-level analysis of predictors of metabolic disease in PLWH and men who are at high risk of acquiring HIV, we found that increased lipopolysaccharide-binding protein, an inflammatory marker indicative of compromised intestinal barrier function, was associated with worse metabolic health." (PMID 34006628, 2021). "Consistent with the previously reported role of inflammation in this relationship, age was positively correlated with 5 of the 14 immune measures that VSURF selected as important predictors of the metabolic disease score, including LBP, CRP, IL-6, ICAM-1, and SAA." (PMID 34006628, 2021). "Effect of SNP in LBP-gene atopy, metabolic diseases and cancer." (PMID 34295331, 2021).
metabolic disorders (continued). "Nevertheless, plasma LBP levels have been investigated in many metabolic disorders, as LBP is synthesized in the liver and initiates the recognition of LPS, delivering LPS to other adaptor molecules to trigger the TLR4 signaling pathway and the production of proinflammatory cytokines." (PMID 33505393, 2020). "Therefore, individuals suffering from obesity, diabetes, and related metabolic disorders also present with highly elevated LBP-levels, which was probably attributed to chronic low-grade inflammation induced by alterations of the intestinal flora together with an increased gut permeability to LPS." (PMID 34295331, 2021). "In this study, we demonstrated that reduced circulating LBP levels correlated with the presence of NAFLD and metabolic diseases in an adult obese population." (PMID 38139003, 2023). "LBP is the initial accessory protein that is expressed to coordinate the interaction of LPS with host TLR4-MD2 receptor complexes; therefore, it is used as a surrogate marker for circulating LPS and the systemic low-grade inflammation typical of metabolic disease." (PMID 36694591, 2022).
tumor (19 papers, 2015 to 2026). "Various studies have found that decreased apoptosis and increased proliferation in metastatic tumor cells are associated with LPS and LBP as indicators of LPS exposure." (PMID 41011853, 2025). "LBP were detected in the cytoplasm of OS cells as well as in tumour-associated macrophage." (PMID 35990515, 2022). "In addition to the positivity of OS cells, LBP was detected in tumour-associated macrophages." (PMID 35990515, 2022). "Lung metastatic foci showed similar pattern of LBP immunostaining compared to the paired primary tumours." (PMID 35990515, 2022). "The present study revealed the LBP expression in OS tissues and highlights their potential contribution to the tumour microenvironment." (PMID 35990515, 2022). "Myofibroblasts bind to LBP-lipopolysaccharide complexes to induce expression of HCC tumor expressed MCP1 (log2 fold change = −7.42) and VCAM1 (log2 fold change = −2.46), which displayed increased expression in the HCC tumors in this study." (PMID 33995488, 2021). "In order to confirm the results that LBP-3 had the highest antitumor activity among the LBP fractions, the effects of LBP fractions on tumor growth in H22 tumor-bearing mice were investigated." (PMID 31139040, 2017). "After a characteristic analysis, the relationship between MW and antitumor activity of LBP was investigated both in vitro using murine hepatoma H22 cells and in vivo using H22 tumor-bearing mice." (PMID 31139040, 2017). "Secondly, we investigated the effect of LBP fractions on tumor growth in H22 tumor-bearing mice to confirm the in vitro results." (PMID 31139040, 2017). "Since tumor-mass reduction often indicates a strong antitumor effect, tumor inhibition rate as an indicator was used to evaluate the antitumor activity of LBP fractions in the present study." (PMID 31139040, 2017). "Moreover, it was observed that LBP was upregulated in primary GC-LM tissues compared to GC-NLM tissues, and LM tissues had even higher LBP expression than primary tumours." (PMID 37789385, 2023). "Lung metastatic tissues showed similar level of LBP compared to paired primary tumours." (PMID 35990515, 2022). "Tumor-bearing mice exhibited several markers of colonic barrier disruption, including dampened expression of tight junction proteins (Cldn1 and Ocln) and elevated circulating lipopolysaccharide binding protein (LBP)." (PMID 35248004, 2022). "In the present study, tumor-bearing animals experienced weight loss (irrespective of food intake), elevated circulating LBP, and elevated splenic cytokines that were subsequently corrected by tumor resection." (PMID 35248004, 2022). "The results indicated that the LBP fraction did not cause immunosuppressive side-effects in the H22 tumor-bearing mice." (PMID 31139040, 2017). "Then, the water-soluble LBP fractions (LBP-2, LBP-3, LBP-4, and LBP-5) were taken to investigate the antitumor activity both using murine hepatoma H22 cells in vitro and using H22 tumor-bearing mice in vivo." (PMID 31139040, 2017). "In vitro study results showed that LBP treatment inhibited tumor cells growth." (PMID 31139040, 2017). "Indeed, in contrast to diagnosed biopsies of patients suffering from metastases characterised by a moderate LBP immunoreactivity, primary tumour biopsies of patients with a local disease showed high percentage of positive cancer cells including average and high immunoreactivity." (PMID 35990515, 2022). "Notably, the vast majority of these relationships were negative associations with the bacteria, spleen cytokines, spleen FISH staining, brain Il-1β, and serum LBP that were all higher in Tumor mice (given that the relative abundance of Lactobacillus was lower in Tumor and Resected mice)." (PMID 35248004, 2022). "Furthermore, LBP could maintain high levels of T cells in tumor tissue, tumor-draining lymph nodes, and peripheral blood." (PMID 36002595, 2022).
tumor (continued). "However, the upregulation of circulating LBP in association with tumour malignancy has not been reported previously." (PMID 25652121, 2015). "The identification of CRP and LBP in this study and IL-6 previously as indicators of response to radiotherapy suggests that inflammation could be an important factor in radiotherapy response either through tumour response or radiotherapy toxicity." (PMID 26425690, 2015). "QRT-PCR showed that the expression of the ACTA2, C1QTNF9, DNAH8, GATM, LBP, and NGF were significantly downregulated in tumor samples." (PMID 36319832, 2022). "Interestingly, in the current study, the LBP expression and the number of M1-polarised macrophages were similarly increased in OS meta- group compared to OS Meta+ group suggesting a potential functional relationship between intra-tumour microbiota and the local immune surveillance by macrophages." (PMID 35990515, 2022). "In the present study, LBP detected in the cytoplasm of cancer cells, was used as an indirect biomarker of LPS exposure and consequently of Gram-negative bacteria in the tumour ecosystem." (PMID 35990515, 2022). "The present study aimed to compare the LBP expression as a biomarker of Gram-negative bacteria exposure in three OS biological cohorts composed by primary tumour tissues of patients with and without metastatic status." (PMID 35990515, 2022). "Lipopolysaccharide binding protein (LBP) was a key serum molecule for TLR4 internalization, which could induce IFN-β expression and involved in tumor immunotherapy response." (PMID 34177903, 2021). "In cachectic mice, F. prausnitzii did not modify the tumor mass, the gut permeability, plasma LBP levels and intestinal markers of the gut barrier function." (PMID 29719601, 2018). "The results showed that LBP-2, LBP-3, LBP-4, and LBP-5 could inhibit tumor growth in H22 tumor-bearing mice by 18.18%, 37.97%, 9.09%, and 14.44%, respectively." (PMID 31139040, 2017).
cancer (16 papers, 2015 to 2025). A tumor composed of atypical neoplastic, often pleomorphic cells that invade other tissues. "LBP, known as an acute-phase protein, has been found to be associated with the progression of multiple types of cancer." (PMID 37789385, 2023). "Interestingly, the results suggested that LBP gene expression was significantly associated with the BMI status of patients (r = 0.178, P < 0.001), which was found to be significantly associated with cancer prognosis." (PMID 32793465, 2020). "The aim of this prospective study was to analyse the value of procalcitonin (PCT) and lipopolysaccharide binding protein (LBP) to predict serious complications and bacteraemia in cancer patients with febrile neutropenia, compared with MASCC score." (PMID 30591812, 2019). "This study has investigated the role of PCT and LBP, compared to MASCC score, as markers for prognosis in adult cancer patients with chemotherapy-associated febrile neutropenia presenting at an ED." (PMID 30591812, 2019). "Notably, BLI analyses showed that pre-modeling with exogenous LBP significantly increased cancer cell colonisation in the liver, even in the first week after intrasplenic injection." (PMID 37789385, 2023). "A recent study has identified LBP in the serum to be a new biomarker of cancer cachexia." (PMID 34002024, 2021). "The results also indicated that LBP gene expression was significantly associated with the BMI status of patients from the LIHC cohort, which was found to be significantly associated with cancer prognosis." (PMID 32793465, 2020). "In addition, we point out the lipopolysaccharide-binding protein as a new biomarker of cancer cachexia related to gut dysbiosis." (PMID 29719601, 2018). "Furthermore, by screening through the criteria of the PPI network, cancer-related pathway and TRS modeling, essential features with gene symbols of EPB41, PSMA1, FGFR3, MRAS, LEP, C7orf46, LOC285000, LBP, ZNF35, SLC30A3, LECT2, RNF7, and DYNC1I1 were identified as PRBs for COAD patients." (PMID 32528533, 2020). "Upregulation of 48 proteins in samples of cancer patients was reported, that included several inflammation/acute phase-related proteins: A1AG1 (ORM1), A1AT (SERPINA1), AACT (SERPINA3), CO4B, CO9, HPT, ITIH4, LBP and SAA1, which upregulation was revealed also in our study." (PMID 26376850, 2015).